CD4 (CD4 molecule)
Diseases named in the same sentence as CD4 in open-access papers (continued):
Sharing a sentence is not in itself a finding about the gene and the disease.
squamous cell carcinoma (continued). "While analyzing the total number of CD4+ T cells, they were more frequently found in squamous cell carcinoma than adenocarcinoma (P < 0.05)." (PMID 26604855, 2015). "Considering tumor types, when control-study groups were compared, inflammation was statistically significant only in adenocarcinoma subtype; intratumoral CD4/CD8 ratio was statistically significant only in squamous-cell carcinoma subtype (respectively, p = 0.0008 and p = 0.0139)." (PMID 38468248, 2024). "A fascinating analysis of the immune landscape in NSCLC using EMT scores showed that EMT was associated with increased levels of immunosuppressive cytokines such as TGF-β and a markedly decreased infiltration of CD4 T-cells in lung AC and CD4/CD8 T-cells in squamous cell carcinoma." (PMID 39547513, 2024). "We found a significant association between PD-L1 expression and smoking intensity, histological type of squamous cell carcinoma, and the infiltration of the immune cells: CD4+ T cells, Foxp3+CD4+ T cells, CD8+ T cells, and M2 macrophages, in the tumour microenvironment." (PMID 38541208, 2024). "VISTA is expressed on tumour-infiltrating lymphocytes (TILs), myeloid-derived suppressor cells and regulatory T cells (MDSCs), regulatory T cells (CD4+CD25+Foxp3+Treg), dendritic cells (DCs), tumour associated macrophages (TAMs/MФ) and neoplastic squamous carcinoma cells." (PMID 36980527, 2023). "In addition, in the analysis of TIICs in 1290 patients with squamous cell carcinoma, immature B cells, CD4+ T cells, CD8+ T cells, mast cells, follicular helper T cells, M1 macrophages, M0 macrophages, neutrophils, eosinophils have certain clinical value for the prognosis of squamous cell carcinoma." (PMID 36611857, 2022). "In their study, the increased risk of skin cancer was correlated with lower CD4 counts in squamous cell carcinoma but not among basal cell carcinoma among HIV-positive patients suggesting that immunosuppression was only partially responsible for the increased incidence of skin cancer." (PMID 29562930, 2018). "In the group of patients with squamous cell carcinoma, the percentage of CD3+CD4+ T lymphocytes was higher (p < 0.001), while the percentage of CD3+CD8+ T lymphocytes was lower (p = 0.02), when compared to volunteers." (PMID 40802351, 2025). "Lastly, by comparing squamous carcinoma and adenocarcinoma cohorts, ΔCEA%, CD3+PD-1+, CD4+PD-1+, and CD4/CD8 are more important in predicting the prognosis of adenocarcinoma patients, while age is more significant for squamous carcinoma patients." (PMID 38451413, 2024). "We examined the TIL and tertiary lymphoid structure (TLS) density in the invading front and inner tumor stroma, and the lymphocyte subpopulation (CD8, CD4, FOXP3) density in 60 squamous cell carcinomas of the lip." (PMID 36900270, 2023). "In the present study, we aimed to investigate the prognostic value of CD3+, CD4+, CD8+, and CD45RO + TILs and their relation to histopathological features in larynx squamous cell carcinoma." (PMID 36319566, 2022). "Formalin-Fixed and Paraffin-Embedded (FFPE) samples from 63 primary larynx squamous cell carcinoma patients were immunostained for CD3, CD4, CD8, and CD45RO expression." (PMID 36319566, 2022). "In headneck squamous cell carcinoma, platelets inhibited T cell proliferation, cytokine production (IFN-γ, TNF-α) of CD4+ T Cells and decreased PD-1 expression on CD4+ and CD8+ T cells." (PMID 34722319, 2021). "A significantly higher percentage of CD3+ T (p < 0.04), CD8+ (p < 0.03), CD8+ CD45RO+ (p < 0.01), CD4+DR+ (p < 0.02, CD8+DR+ (p < 0.05), and CD8+ CD39+ (p < 0.02) cells were found in TT from an adenocarcinoma than in TT from a squamous cell carcinoma." (PMID 27689405, 2016). "Regarding the activation marker CD69, both in CD19+ B lymphocytes and in CD3+CD4+ T lymphocytes, the group with squamous cell carcinoma presented higher percentages, with p indicating differences for CD19+ B lymphocytes (p = 0.01) and T lymphocytes CD3+CD4+ (p = 0.03)." (PMID 40802351, 2025).
squamous cell carcinoma (continued). "In the squamous cell carcinoma group not receiving PD-1/PD-L1 inhibitor, the immunohistochemical expression of YTHDF1 was significantly negatively associated with CD4 and CD8 expression." (PMID 36479088, 2022). "The expression, in both tumor and stromal compartments, of CD4 (p = 0.024 and p = 0.008, respectively), CD8 (p = 0.044 and p = 0.008, respectively), and LAG3 (p = 0.008, in both cases) were higher in adenocarcinoma (ADC) than in squamous cells carcinoma (SCC) patients." (PMID 27463005, 2016). "The immune cell density (CD3, CD4, CD8, CD45RO, CD204, PD1) added prognostic value in squamous cell carcinoma (LUSC) and LUAD with 0-5% NAA (NAA-), but not in LUAD NAA+." (PMID 37182191, 2023). "The T cells were CD4- and CD8-positive, predominantly intratumoral, and the CD4:CD8 ratio was 1:1 for 75% of the undifferentiated subtype and 89% for differentiated non-keratinized squamous cell carcinoma." (PMID 38611634, 2024).
vasculitis (46 papers, 2010 to 2025). "A 6-month course of valaciclovir therapy has been shown to mediate a 28% reduction the proportion of CD4+CD28- T cells in patients undergoing immunosuppressive therapy for vasculitis and was associated with enhanced immune response to pneumococcal vaccination." (PMID 41460874, 2025). "All patients with HIV-associated vasculitis had a median CD4+ count of <200 cells/μL, and HIV-1 RNA was below the LLOQ; this differed from those with nonatherosclerotic and atherosclerotic vasculopathy." (PMID 28931222, 2017). "Recent evidence also showed a deficiency of CD4 + CD25+ regulatory T (Treg) cells in HCV-related MC patients with active vasculitis." (PMID 26129991, 2015). "In this respect, the use of Valacyclovir as anti-CMV treatment in patients with Antineutrophil Cytoplasmic Antibody (ANCA)-Associated Vasculitis was shown not only to suppress CMV reactivation but was also associated with a reduction of the CD4+CD28− T-cell frequency." (PMID 34576140, 2021). "Data from re-engraftment studies have revealed that vasculitis-causing T cells acquire tissue residency and build autonomous, self-sufficient inflammatory lesions, where repopulation of inflammatory CD4+ T cells is maintained from tissue-resident memory populations." (PMID 33717054, 2020). "It is caused by vasculitis determined by humoral factors with subsequent inflammatory cell accumulation, mainly T CD4+ and B cells, which infiltrate myocytes leading to its vacuolization and degeneration (mainly in the skeletal muscles, rarely in the smooth muscles)." (PMID 31734477, 2019). "The use of IL-7R as a surrogate marker for TCF1hi CD4+ T cells revealed that these stem-like CD4+ T cells are essential for driving transferable and persistent vasculitis in serial transplantation experiments." (PMID 40634636, 2025). "The characteristic histopathologic lesion is vasculitis with vascular and perivascular infiltration of predominantly CD4 and CD8 T lymphocytes and macrophages." (PMID 37168237, 2023). "Activated T lymphocytes promote arterial inflammation, and a variety of T lymphocyte subsets and cytokines are involved in the pathogenesis of TA.CD4+ T lymphocytes are also known as key cell participants in vasculitis." (PMID 35006213, 2021). "Specifically, CD8+ T cells with regulatory function, CD8+ Treg cells, are defective in GCA patients, failing to dampen CD4+ T cell function in vasculitis." (PMID 33717054, 2020). "Given that autoreactive CD4+ and CD8+ cells are present in vasculitis patients, experimental passive transfer studies have defined a role for CD4+ and CD8+ cells in AAV." (PMID 33251233, 2020). "In vasculitis complication of RA, CD4+CD28− T cells were observed only in patients infected with HCMV, suggesting a role for HCMV in boosting T cell autoreactivity." (PMID 23372569, 2013). "Cytoplasmic positivity for MMP2 was occasionally observed in mild cases of ACR and AMR, but without significant associations with vasculitis, the Quilty effect, or inflammatory marker expression (CD4, CD8, and CD68)." (PMID 41009699, 2025). "Humanized mouse models have shown that dual immunotherapy of PD‐1/CTLA‐4 inhibitors induces severe interstitial nephritis and vasculitis compared with monotherapy, with CD4+ T cell aggregation in the affected tissues, consistent with the renal pathological phenotype in patients." (PMID 40787068, 2025). "Limiting CMV turnover could slow immune ageing - a small phase I study found improved vaccination response and reduced number of senescent CD4+ T cells in patients with vasculitis when treated with the antiviral valacyclovir." (PMID 39399503, 2024). "Furthermore, anti-CD4 monoclonal antibody therapy for SLE significantly reduced the incidence of vasculitis, and glomerulonephritis, and significantly lowered the levels of antinuclear antibody, total IgG, and anti-dsDNA33." (PMID 35908050, 2022). "How this reduction in CD4+ Treg cells leads to vasculitis is unresolved." (PMID 33072134, 2020).
vasculitis (continued). "In addition to a pathogenic role for ANCA, cellular immunity is also considered to be important in ANCA vasculitis, with a role for effector CD4+ cells demonstrated in a murine model." (PMID 28138552, 2017). "MPO-ANCA reduced secretion of antiinflammatory IL-10 by monocytes (and may hence further foster local inflammation) and also induced development of macrophages that instruct CD4+ T cells, which could contribute to the tissue fibrosis observed in vasculitis." (PMID 28138552, 2017). "Interestingly, CD4+CD28− T cells described in RA vasculitis were found only in human cytomegalovirus-seropositive, but not in HCMV-negative RA patients, and their specificity was predominantly directed toward HCMV antigens." (PMID 23372569, 2013). "CD4+ cells trigger cytotoxic reaction of CD8+ cells against antigens and may cause vasculitis, cerebritis or both." (PMID 20637120, 2010). "The DCs significantly decreased vasculitis and MPO-specific immunity, including effector CD4 T cell activation, proliferation, survival and pro-inflammatory cytokine production, as well as CD8 T cell and B cell responses." (PMID 34394071, 2021). "Inhibiting the JAK/STAT signaling pathway with a small molecule inhibitor targeting JAK1/3 is highly effective in suppressing vasculitis, including the IFN-γ-producing CD4+ T cells." (PMID 33717054, 2020). "The study also observed various cellular communication patterns of vasculitis at different time points and identified co-expression modules related to ribosomal function, cell proliferation, and immune responses in CD19+ B cells, CD4+ T cells, CD8+ T cells, CD14+ monocytes, and CD16+ monocytes." (PMID 40207219, 2025). "In anti‐neutrophil cytoplasmic autoantibody (ANCA) vasculitis, Tregs possess diminished suppressive capacity, which has been attributed to the expression of a FOXP3 splice‐variant lacking exon 2 in T cells (FOXP3Δ2 CD4+ T cells)." (PMID 36381498, 2022). "Comparative studies of CD4+ and CD8+ T cells, which are responsible for fundamentally different effector pathways, may shed light on the state of chronic stimulation of the adaptive immune system in this form of vasculitis." (PMID 33072134, 2020). "Accordingly, patients suffering from systemic vasculitis with renal involvement had a significantly lower expression of CD122 on Tregs when compared to patients with localized, nonrenal vasculitis (CD4+CD25+FoxP3+ Tregs: %CD122+ 34 ± 19% versus 49 ± 10%, P = 0.04)." (PMID 24648606, 2014). "The various types of HIV-associated vasculopathy differed by ART status and CD4+ count; for example, no patient with atherosclerotic vasculopathy had started ART in the last 6 months, compared with 43% of the nonatherosclerotic and 67% of the HIV-associated vasculitis subtypes." (PMID 28931222, 2017).
chronic lymphocytic leukemia (45 papers, 2004 to 2025). "An enrichment of antigen-experienced memory and effector CD4+ T-cells accompanied by a relative loss of naïve CD4+ T-cells has been repeatedly observed in chronic lymphocytic leukemia (CLL)." (PMID 32457353, 2020). "Findings that FasL+ B-chronic lymphocytic leukemia (B-CLL) cells kill a susceptible CD4+ T-cell leukemia cell line provided the first direct evidence implicating B cells in the induction of T cell apoptosis." (PMID 28424702, 2017). "Notably, an elevated level of CD4+ Tcm cells has been associated with poor prognosis in chronic lymphocytic leukemia." (PMID 41209008, 2025). "The first direct evidence that human B cells could induce TH cell apoptosis was demonstrated using FasL+ B-chronic lymphocytic leukemia (B-CLL) cells to kill a susceptible CD4+ T-cell leukemia line." (PMID 25852690, 2015). "Idelalisib resulted in a CD4:CD8 ratio in chronic lymphocytic leukemia (CLL) patient-derived CAR-T cells that was closer to the ratio in healthy donors." (PMID 36701037, 2023). "We detected cytotoxic, programmed cell death protein-1 (PD-1) and EOMES co-expressing CD4+ T cells in lymph nodes (LNs) of patients with chronic lymphocytic leukemia (CLL) or diffuse large B-cell lymphoma." (PMID 33526861, 2021). "PD-1 disruption of stable synapse formation in vitro was also reported for CD8+ T cells from chronic lymphocytic leukemia models or CD4+ T cells from AND TCR transgenic mice." (PMID 33980853, 2021). "For instance, one report demonstrated that CD8+ and CD4+ T cells are unable to form proper immune synapses with chronic lymphocytic leukemia (CLL) cells, which hindered anti-tumor activity." (PMID 33717081, 2021). "Despite abundant phenotypical data characterizing CD4+ T cells in chronic lymphocytic leukemia (CLL), their role in disease development and progression is controversial and poorly understood." (PMID 33526861, 2021). "TIGIT expression was also found to be significantly increased in CD4+ T cells from chronic lymphocytic leukemia patients, and an increased number of TIGIT+ CD4+ T cells was found in patients with advanced disease stage." (PMID 31681269, 2019). "CD4+/PD-1+ T lymphocytes were found to be in close contact with PD-L1+ chronic lymphocytic leukemia cells and the activated PD-1/PD-L1 axis led to decreased production of IL-4 from CD4+ T lymphocytes." (PMID 30069490, 2018). "In chronic lymphocytic leukemia, levels of circulating CD4+CD39+ T cells significantly increased and correlated with advanced stage of the disease." (PMID 28388539, 2017). "In the setting of chronic lymphocytic leukemia, both CD4+ T cells and CD8+ T cells express high-level CD39 and furthermore, CD39 is associated with advanced disease stage." (PMID 28690614, 2017). "T-cell dysfunction is a hallmark of chronic lymphocytic leukemia (CLL), but the extent to which individual CD4+ or CD8+ T-cell subpopulations influence specific clinical events remains unclear." (PMID 40313965, 2025). "A study with chronic lymphocytic leukemia patients found elevated total lymphocyte count and unchanged CD4+ T cell count after 45–60-min exercise, and another study with pediatric lymphoblastic leukemia survivors found increased neutrophil count after 30-min exercise." (PMID 36714311, 2022). "Pallasch and colleagues demonstrated that antagonistic anti-CD200 antibody could promote chronic lymphocytic leukemia cell-induced proliferation of antigen-specific T cells and reduce the proportion of CD4+CD25highFoxP3+ cells." (PMID 22621248, 2012). "Moreover, a 10-year follow-up of two patients with chronic lymphocytic leukemia who achieved remission after treatment with CD19 CAR-T cells uncovered that the engineered population still present at later time points was dominated by CD4 T lymphocytes." (PMID 36593069, 2023). "In line with our findings, high CD38 expression levels have also been reported in the CD4+ Tcm cell subset of patients with B cell chronic lymphocytic leukemia (CLL)." (PMID 32093678, 2020).
chronic lymphocytic leukemia (continued). "The U.S. Food and Drug Administration recently approved lisocabtagene maraleucel (liso‐cel) for the treatment of CLL and small lymphocytic lymphoma (SLL); liso‐cel, a CD19 targeted CAR T‐cell therapy, is administered as equal doses of CD8 and CD4 CAR T cells." (PMID 39224539, 2024). "First, in patients with chronic lymphocytic leukemia (CLL), AML, or adult acute lymphoblastic leukemia (ALL), TIGIT is commonly upregulated on CD4+ T cells, CD8+ T cells, Foxp3 + γδ T cells, or NK cells compared with healthy individuals." (PMID 37291608, 2023). "have demonstrated the enduring impact of CAR-T cell therapy in treating chronic lymphocytic leukemia (CLL), particularly in tracking the persistence and development of CD4+ CAR-T cells over a decade." (PMID 38090577, 2023). "Finally, cytotoxic Eomes+ CD4 T cells can mediate anti-tumor activity as shown in models of chronic lymphocytic leukemia (CLL)." (PMID 36756120, 2023). "Multi‐color flow cytometry analysis of absolute and relative numbers of CD4+ and CD8+ T‐cells and their subsets in patients with both indolent and progressive chronic lymphocytic leukemia." (PMID 36440594, 2023). "In chronic lymphocytic leukemia (CLL), STAT3 is required to PD-L1 expression and IL-10 production which in turn seems to be responsible for PD-1 expression in CD4+ and CD8+ T-cells." (PMID 31480382, 2019). "Ibrutinib, a Bruton's tyrosine kinase inhibitor, was shown to down-regulate PD-L1 expression on tumor cells and PD1 in CD4+ and CD8+ T cells via inhibition of STAT3 and also decreased IL-10 production by chronic lymphocytic leukemia (CLL) cells in patients." (PMID 30420856, 2018). "In fact, patients with chronic lymphocytic leukemia, who were infused using CAR-T cells a decade ago and achieved complete cancer remission, exhibited highly activated CD4+ T cells that dominated the CAR-T cell population, corroborating a long-persisting CD4+ T cells." (PMID 38685033, 2024). "At the 6‐month timepoint, the longevity of the CD4+ T‐cell responses in these latter groups (solid organ transplant and chronic lymphocytic leukemia) was not sustained as well as responses seen in healthy individuals or the other immunocompromised groups." (PMID 36825370, 2023). "Moreover, in B-cell CLL, CD38 is also expressed on CD4+ Tn and Tcm subsets, and the proportion of CD38+ B cells is a predictor of clinical outcome." (PMID 32093678, 2020). "Moreover, recent clinical evidence has shown higher relative CD4 and CD8 counts in patients with chronic lymphocytic leukemia (CLL) are independent predictors for survival, emphasizing the importance of immune reconstitution in survival." (PMID 29617362, 2018). "In the present study, we have examined the kinetics and magnitude of expression of the CD28 and CD152 molecules on unstimulated and anti-CD3+rIL-2-stimulated peripheral blood CD4+ and CD8+ T cells in patients with chronic lymphocytic leukaemia (B-CLL) and controls." (PMID 15138491, 2004). "Interestingly, a distinct role for TIGIT has been suggested in both solid and hematological tumors, as demonstrated by its high expression on CD4+ but not CD8+ T cells in chronic lymphocytic leukemia (CLL)." (PMID 39684559, 2024). "PRDM1 gene expression was consequently significantly upregulated in CD4+ and CD8+ T-cells in chronic lymphocytic leukemia patients but not in their leukemic B-cells." (PMID 30654767, 2019). "However, despite a decrease in the total number of CD4+ and CD8+ T cells, their differentiation status did not change after 1 year of VEN-based therapy in patients with chronic lymphocytic leukemia." (PMID 38812504, 2024).